CCL11 (C-C motif chemokine ligand 11)
Diseases named in the same sentence as CCL11 in open-access papers (continued):
Sharing a sentence is not in itself a finding about the gene and the disease.
lung fibrosis (10 papers, 2011 to 2025). "Ccl11-deficient mice and neutralizing Ccr3 reduce pulmonary fibrosis, decreasing eosinophilia and neutrophilia, and profibrotic cytokine." (PMID 39768150, 2024). "The implication of eotaxins in lung fibrosis are poorly understood, nonetheless, CCL11 is increased in experimental lung fibrosis while CCL11 deficient mice are protected and both CCL11, CCL24 and CCL26 are able to influence fibroblast behavior." (PMID 34093523, 2021). "BAL CCL11 levels significantly correlate with eosinophil numbers in sulfur mustard gas-induced pulmonary fibrosis, indicating its role in eosinophil recruitment during lung fibrosis." (PMID 39768150, 2024). "However, local depletion of CD11c+ myeloid cells increases CCL4 and CCL11 in the lungs, which are critical for leukocyte chemoattraction and lung fibrosis." (PMID 39582275, 2024). "Bleomycin stimulation induces CCL11 production in human lung fibroblasts and epithelial cells in vitro, suggesting their involvement in eosinophil recruitment in bleomycin-induced pulmonary fibrosis." (PMID 39768150, 2024). "Furthermore, CCL11 appears to be involved in lung fibrosis, a central feature for tissue remodeling observed in asthmatic patients, as its depletion prevented pulmonary fibrosis in mice." (PMID 37860000, 2023). "Furthermore, consistently unique cytokine expression patterns of regenerative and growth factors (CCL2, CCL11, IL6, IL12B, and CXCL8) may indicate activation of pulmonary fibrosis signaling pathways after aberrant inflammatory response." (PMID 35145507, 2021). "The lack of changes in Cxcl13, Ccl11, Ccl19, Xcl1, and Cxcl5 mRNA levels may be due to differences in bleomycin-induced pulmonary fibrosis and IPF, although models of bleomycin-induced pulmonary fibrosis are the most common experimental models for investigating IPF." (PMID 37122736, 2023).
multiple sclerosis (10 papers, 2015 to 2025). A progressive autoimmune disorder affecting the central nervous system resulting in demyelination. "Increased CCL-11 also plays a role in neuroinflammatory disease including multiple sclerosis." (PMID 32887304, 2020).
nasal polyps (9 papers, 2016 to 2025). "Notably, mRNA expression of CCL4, but not other well-known eosinophil-associated chemokines, such as CCL5, CCL11, and CCL26, was significantly higher in nasal polyps of patients with ECRS than in uncinate tissues of the same patients." (PMID 36555793, 2022). "Recently, CCL4, CCL5, CCL11, and CCL26 expressions were found to be higher in nasal polyps than in uncinate process tissue in the same patients with ECRS." (PMID 36555793, 2022). "Levels of IL-4, IL-5, IL-13, and ECP and the eotaxins CCL11, CCL24, and CCL26 were elevated in the nasal polyps of patients with eCRSwNP or noeCRSwNP." (PMID 35747690, 2022). "The expression of CCL4 and other eosinophilic chemoattractants (CCL5, CCL11, and CCL26) was reported to be increased in nasal polyps compared with that in uncinate process tissues of the same patients with ECRS." (PMID 36555793, 2022). "The eosinophilic chemo-attractants CCL4, CCL5, CCL11, and CCL26 were increased in nasal polyps compared with uncinate process tissues." (PMID 32085629, 2020). "In nasal polyps, immunoreactivity of the chemokine ligand (CCL) eotaxin subfamily comprising eotaxin-1 (CCL11), eotaxin-2 (CCL24), and eotaxin-3 (CCL26) was noted." (PMID 30778348, 2019). "Chemokines secreted by epithelial cells include eotaxin-1 (CCL11), eotaxin-2 (CCL24) and eotaxin-3 (CCL26) which have been demonstrated in increased numbers in nasal polyps as compared to healthy controls." (PMID 29376948, 2016). "Notably, CCL4 expression, but not CCL5, CCL11, or CCL26, was found to be significantly increased in nasal polyps from patients with ECRS associated with eosinophil infiltration as well as in BEAS-2B cells co-incubated with eosinophils." (PMID 36555793, 2022).
Stroke (9 papers, 2012 to 2024). Sudden impairment of blood flow to a part of the brain due to occlusion or rupture of an artery to the brain. "In the hypertensive group, CCR2 rs1799864, CCR5 rs1799987 and CCL11 rs4795895 were nominally associated with increased risk of stroke." (PMID 22769019, 2012). "Polymorphisms in the CCL-11 gene are associated with stroke." (PMID 32887304, 2020). "After having analyzed the impact of CCL11 on both adolescent and adult mice as well as its underlying way of action, we next set out to study a possible therapeutic effect of CCL11 receptor blockage after stroke." (PMID 31888056, 2019). "CCL11 levels at 24 hours after ischemic stroke were significantly associated with in-hospital mortality at patient discharge, and lower CCL11 levels predict stroke severity and can be used as a prognostic marker to predict acute and long-term functional impairment in ischemic stroke patients." (PMID 39206161, 2024). "Our group has previously reported that, when using machine learning analysis, CCR3 expression was a predictor of both infarct and edema volumes, while CCL11 was a predictor of edema volume from the blood of human stroke patients." (PMID 38332938, 2024). "Similar analysis of genes in the Disease and Function categories indicated that female MMP-3 KO stroke brains had decreased expression of leukocyte migration genes Ccr1, Pecam1, Mmp9, Ccl6, Icam2, and Ccl11." (PMID 39000490, 2024). "First, we focus on soluble dipeptidyl peptidase 4 (s-DPP4) and C–C motif chemokine 11 (CCL11) as biomarkers and potential therapeutics for post-stroke cognition that have been previously reported on in the context of stroke and in cognition." (PMID 37280551, 2023). "The therapeutic potential of the CCL11 pathway under ischemic conditions is underscored by using the CCL11 inhibitor SB297006, which not only reverses the CCL11-induced aggravation of brain injury but also yields neuroprotection in adult stroke mice." (PMID 31888056, 2019). "CCL11 has recently been shown to differentially affect cell survival under various pathological conditions including stroke." (PMID 31888056, 2019). "Thereafter, therapeutic effects of antagonizing CCL11 were analyzed with regard to post-stroke acute brain injury." (PMID 31888056, 2019). "The work presented herein indicates that CCL11 differentially affects post-stroke brain injury and neuroregeneration, depending on the age of mice exposed to stroke." (PMID 31888056, 2019). "The present study thus highlights the importance of age in a possible therapeutic setting against stroke, when interfering with the CCL11 signaling pathway." (PMID 31888056, 2019). "Our study, for the first time, demonstrates CCL11 to be a key player in mediating secondary cell injury under stroke conditions." (PMID 31888056, 2019). "With cerebral ischemia usually known to activate microglia resulting in a state of inflammation, decreased numbers of microglia in adult stroke animals after treatment with CCL11 are surprising." (PMID 31888056, 2019). "As such, we herein demonstrated CCL11 to promote post-stroke neurogenesis and gliogenesis in adolescent mice, whereas elderly mice displayed aggravated acute brain injury, impaired functional recovery and inhibited neurogenesis." (PMID 31888056, 2019). "The present study, for the first time, demonstrates the controversial effects of CCL11 in both adolescent and adult stroke mice." (PMID 31888056, 2019). "Of note, CCL11 delivery lasted until week one post-stroke, most likely affecting the generation and differentiation of new-born cells." (PMID 31888056, 2019). "As stated afore, a mutual interaction between peripheral and central immune responses under stroke conditions initiated by systemic CCL11 cannot be completely excluded." (PMID 31888056, 2019).
Stroke (continued). "As such, we studied the effect of ectopic CCL11 in both adolescent and adult mice exposed to focal cerebral ischemia with an observation period of four weeks, focusing on post-stroke brain injury, inflammation, neuroregeneration, and neurological recovery." (PMID 31888056, 2019). "Likewise, post-stroke neurological recovery after four weeks was significantly impaired in adult mice whilst CCL11 was present." (PMID 31888056, 2019). "Consequently, both peripheral (blood) and central (brain) immune responses upon treatment with CCL11 were analyzed in the two mice groups, using flow cytometry on day 7 post-stroke." (PMID 31888056, 2019). "Likewise, the subset of T cells in the brain is also significantly increased upon CCL11 treatment in adolescent mice exposed to stroke." (PMID 31888056, 2019). "Since the present work focused on performing a proof-of-concept study on CCL11 in adult stroke mice and thus indirectly implied a therapeutic hypothesis, further elucidating the precise role of microglia under such conditions was beyond the scope the present work." (PMID 31888056, 2019). "Consequently, ectopic application of CCL11 in elderly mice might even result in higher mortality of such stroke mice." (PMID 31888056, 2019). "Indeed, CCL11 promotes neuroregeneration in neonatal stroke mice." (PMID 31888056, 2019). "While the study focused on these key proteins due to their established roles in stroke recovery, other proteins that showed altered regulation across different groups, such as IMP-1 and CCL11, were also noted." (PMID 38178130, 2024). "We therefore studied the effect of ectopic CCL11 on both adolescent (six-week) and adult (six-month) C57BL6 mice exposed to stroke." (PMID 31888056, 2019). "The expression of ligands for CCR3, CCL5, CCL11 and CCL24, have been studied in stroke models." (PMID 38332938, 2024). "As such, CCL11 significantly aggravates brain injury in adult stroke mice, without affecting infarct volumes in adolescent mice." (PMID 31888056, 2019). "Even though cytokines such as CCL11 are likely to interfere in this process because of their natural biochemical properties, the influence of CCL11 on post-stroke inflammation have not been sufficiently studied, yet." (PMID 31888056, 2019). "Immunohistochemical analysis in adult mice, however, did not only show no stimulatory effect of CCL11 on post-stroke neurogenesis but rather displayed a significantly decreased level of neurogenesis in these animals." (PMID 31888056, 2019). "Although microglial activation in both adolescent and adult mice treated with CCL11 was not changed at four weeks post-stroke, it stands to reason that post-stroke regulation of gliogenesis and neurogenesis is likely to be a consequence of microglial activity." (PMID 31888056, 2019). "Although CCL11 aggravated both acute brain injury and neurological impairment in adult stroke mice, the latter does not necessarily imply an increased neuronal cell loss in the long run." (PMID 31888056, 2019). "Nevertheless, the CDK5/p35 pathway was not affected by CCL11, neither in adolescent nor in adult stroke animals." (PMID 31888056, 2019). "Adult mice did not only show no stimulation of neurogenesis after CCL11 treatment, they rather displayed a decreased level of neurogenesis four weeks after stroke." (PMID 31888056, 2019). "In adolescent mice, CCL11 did not affect acute brain injury, as depicted by infarct volumetry on day 1 post-stroke." (PMID 31888056, 2019). "Since CCL11 might affect post-stroke brain injury in an age-dependent manner, we first analyzed whether or not ectopic CCL11 affects infarct volume at the acute stage of stroke." (PMID 31888056, 2019). "Likewise, post-stroke gliogenesis was significantly increased in adolescent mice treated with CCL11 in comparison to controls, whereas no impact of CCL11 on gliogenesis was observed in adult animals." (PMID 31888056, 2019).
Anxiety (8 papers, 2016 to 2025). Intense feelings of nervousness, tension, or panic often arise in response to interpersonal stresses. "After evaluating common psychiatric disorders separately, mood disorders and anxiety confirmed their association with lower concentrations of CCL11 in abstinent AUD patients." (PMID 28149283, 2016). "In healthy hospital workers, anxiety scores were found inversely associated with levels of CCL2, CCL5, CCL11, and IL-6." (PMID 34863117, 2021). "Therefore, female abstinent patients diagnosed with lifetime anxiety (N = 5) and/or displayed the lowest concentrations of CCL11 [26.38 (95% CI = 16.47–36.29) pg/mL]." (PMID 28149283, 2016). "Thus, patients with mood disorders (N = 42) and/or anxiety (N = 16) had lower CCL11 concentrations than non-comorbid patients being more evident in women." (PMID 28149283, 2016).
Crohn disease (8 papers, 2007 to 2025). A gastrointestinal disorder characterized by chronic inflammation involving all layers of the intestinal wall, noncaseating granulomas affecting the intestinal wall and regional lymph nodes, and transmural fibrosis. "It is known that CCL11 is implicated in Th2 inflammatory diseases, and it has recently been reported that CCL11 gene expression can be a predictive marker for ustekinumab response in patients with Crohn’s disease." (PMID 38791570, 2024).
lung cancer (8 papers, 2012 to 2026). A malignant neoplasm involving the lung. "In lung cancer, eosinophils demonstrate complex and context-dependent functions, shaped by chemokines, cytokines, and tumor-derived signals such as CCL11 and IL-33." (PMID 42131323, 2026). "In contrast, CCL11 and IP-10 levels in lung cancer patients were much lower than the levels detected in TB and TP groups." (PMID 23028695, 2012). "Furthermore, CCL11 has been shown to promote lung cancer metastasis by way of Epithelial to Mesenchymal Transition, a hallmark pro-metastatic pathway." (PMID 38554160, 2024). "Bone marrow-derived suppressor cells (MDSC), through CCL11, activate ERK/AKT signaling, inducing epithelial–mesenchymal transition and promoting lung cancer metastasis." (PMID 38305920, 2024). "Based on these results, we may surmise that CCL11 and IP-10 are specifically increased in plasma from pulmonary tuberculosis and tuberculous pleurisy patients, while CCL8 and CCL2 are specifically decreased when compared with lung cancer controls." (PMID 23028695, 2012).
melanoma (8 papers, 2019 to 2025). A malignant, usually aggressive tumor composed of atypical, neoplastic melanocytes. "In HCC, similar to observations in melanoma, CCL11-expressing tumors demonstrate that IL-5/CCL11 co-stimulation effectively recruits tumor-associated eosinophils, potentially mediating both immune evasion and tumoricidal effects." (PMID 40429807, 2025). "In contrast to other proteins such as CCL11 and LYZ, whose roles in melanoma are relatively well-established, CD72 represents a less-characterized but promising target." (PMID 41148223, 2025). "For example, Sitagliptin treatment improves anti-tumour responses via enhanced CCL11-mediated eosinophil migration in hepatocellular carcinoma mouse models, and promotes CXCL9- and CXCL10-mediated dendritic cell trafficking to melanoma tumours." (PMID 33143089, 2020). "Most secreted factors (TNFα, GM-CSF, G-CSF, PDGF-BB, CCL5, CCL11, IL-3, IL-6) were not induced by exogenous IFNγ in our panel of melanoma cells, confirming the complex inflammatory signaling profile of de-differentiated PD1 PROGs with intrinsic IFNγ signaling." (PMID 36934113, 2023). "We next assessed whether IL-33 induced the expression of eosinophil-attracting chemokines (CCL11, CCL24, CCL26, and CCL5) in melanoma cells and found significant up-regulation of CCL5 and CCL24." (PMID 31717819, 2019). "Neither CCL11 nor CCL26 were expressed by melanoma cells (data not shown)." (PMID 31717819, 2019).
parasitic infections (8 papers, 2017 to 2025). "Among the differentially expressed genes, we identified CCL11 (C-C Motif Chemokine Ligand 11), which is known for its role in attracting eosinophils that is involved in allergic reactions and parasitic infections." (PMID 41149648, 2025). "The clear upregulation of CCL2, CCL12 and CCL11 after parasitic infection implies an additional importance in eosinophil mobilisation." (PMID 34310619, 2021). "Serum levels of IL-6, IL-27, CCL3, CCL5, CXCL10, CCL11, and CCL17 in patients with different parasitic infection profiles living in the rural community of Brejo do Amparo, Januária, Minas Gerais, Brazil." (PMID 33777015, 2021).
prostate carcinoma (8 papers, 2016 to 2025). A carcinoma that arises from epithelial cells of the prostate gland. "Although the prognostic significance of CCL11 in prostate cancer remains undefined, these findings suggest its potential utility as a diagnostic biomarker for distinguishing between normal and pathological prostate conditions." (PMID 40429807, 2025). "Taken together, these results indicate that AP-1 and NF-κB play a central role in the transactivation of scf, ccl5 and ccl11 induced by PKD2 or PKD3 in prostate cancer cells." (PMID 30841931, 2019). "Depletion of PKD2 and PKD3 in prostate cancer cells significantly decreased binding of p65, c-Jun and c-Fos to the scf, ccl5, and ccl11 promoter." (PMID 30841931, 2019). "Moreover, the serum protein biomarker CCL11 (eotaxin-1), a potent chemotactic agent for basophils, is elevated in individuals with prostate cancer, highlighting its role in regulating immune responses and advancing tumor progression." (PMID 39678517, 2024). "Taken together, these data suggested that PKD2/3-regulated SCF, CCL5 and CCL11 secretion in prostate cancer cells may be the key factors that mediated migration and recruitment of MCs in tumor microenvironment." (PMID 30841931, 2019). "To further clarify whether PKD2/3 mediated chemotactic migration of MCs through upregulation of SCF, CCL5, and CCL11 in prostate cancer, we performed migration assay for P815 MCs in a transwell plate." (PMID 30841931, 2019). "Moreover, PKD2/3 depletion not only reduced SCF, CCL5 and CCL11 expression in prostate cancer cells but also inhibited angiogenic factors in MCs." (PMID 30841931, 2019). "Recent work in prostate cancer identified that PKD2 or PKD3 knockdown results in decreased expression and secretion of pro-inflammatory chemokines SCF, CCL5 and CCL11 in two prostate cancer cell lines, with the proteins contributing to the chemotactic migration of mast cells in vitro." (PMID 38323010, 2024). "To examine whether Erk1/2 signaling is required for PKD2/3 induced -SCF, CCL5, and CCL11 expression in tumor cells, we first analyzed the interaction of endogenous PKD2 or PKD3 with Erk1/2 in prostate cancer cells." (PMID 30841931, 2019). "Given that multiple autocrine or paracrine chemokines such as SCF, CCL5 and CCL11 mediated MCs migration and recruitment, so we verified whether PKD2 or PKD3 could regulate these chemokines expression in the prostate cancer cells." (PMID 30841931, 2019).
airway hyperresponsiveness (7 papers, 2011 to 2022). "It is reported that a number of chemokines such as CCL2, CCL5, CXCL10 are associated with RSV-induced airway hyperresponsiveness and CCL11, CCL17, and CCL 22 are involved in the development of pulmonary eosinophilia with RSV infection." (PMID 21980478, 2011). "Following OVA sensitization, HRV infection triggers eosinophilic inflammation and airway hyperresponsiveness, along with increased expression of mucins (Muc5AC and Muc5B), eotaxin-1/CCL11, IL-4 and IL-13." (PMID 30513770, 2018). "Ninety-six h after infection, RV1B-induced airways hyperresponsiveness is dependent on CCL11/eotaxin-1-mediated eosinophilic airway inflammation." (PMID 21637773, 2011).